INMT-MINDY4 (INMT-MINDY4 readthrough (NMD candidate))
Synonyms: INMT-FAM188B
Gene: Protein-coding gene on chromosome 7 (30,752,137 to 30,892,081, forward strand). Ensembl gene ENSG00000254959.
Genetic constraint (gnomAD): Missense variants: 139 observed, 157.91 expected, observed/expected ratio (o/e) 0.88, 90% interval 0.77 to 1.01. Synonymous variants: 68 observed, 66.07 expected, observed/expected ratio (o/e) 1.03, 90% interval 0.85 to 1.26.